LRP6 (LDL receptor related protein 6)
Diseases named in the same sentence as LRP6 in open-access papers (continued):
Sharing a sentence is not in itself a finding about the gene and the disease.
renal clear cell carcinoma (1 paper, 2024). "Moreover, we found that LRP6 was significantly associated with the prognosis of renal clear cell carcinoma." (PMID 38226972, 2024). "Here, we found that LRP6 was significantly associated with the expression of ferroptosis-related genes, and whether LRP6 can influence the progression of kidney clear cell carcinoma through the regulation of ferroptosis requires further confirmation." (PMID 38226972, 2024). "This suggests that LRP6 may affect the occurrence and development of renal clear cell carcinoma by regulating ferroptosis." (PMID 38226972, 2024). "Finally, we also found a significant correlation between the expression of LRP6 and the sensitivity to common drugs used in kidney clear cell carcinoma treatment." (PMID 38226972, 2024).
retinal degeneration (1 paper, 2015). Degeneration of the retina. "The activation of canonical Wnt signaling might contribute to the focal retinal degeneration of mouse models with Ccl2 and Cx3cr1 deficiency, and intravitreal anti-LRP6 antibody therapy might be beneficial via deactivation of the canonical Wnt pathway." (PMID 26476672, 2015).
sarcoma (1 paper, 2017). A usually aggressive malignant neoplasm of the soft tissue or bone. "Furthermore, Nystatin also increased LRP6 cell surface levels in two other Wnt autocrine sarcoma cell lines, A204 and A3243, and decreased uncomplexed β-catenin protein levels in these cells." (PMID 28966723, 2017).
sudden cardiac death (1 paper, 2021). "However, the association between genetic variations of LRP6 and sudden cardiac death (SCD) remains unknown." (PMID 35187114, 2021).
teratocarcinoma (1 paper, 2022). A germ cell tumor characterized by the presence of an embryonal carcinoma component and a teratoma component. "This promotes binding of DAB2 to LRP6 and association with clathrin, thereby inhibiting the interaction of LRP6 with Axin and in turn inhibiting Wnt signalling resulting in reduced in vivo tumorigenesis as described in F9 teratocarcinoma cells." (PMID 36614139, 2022).
tongue cancer (1 paper, 2017). A malignant neoplasm affecting the tongue. "Notably, our results showed that the increased expression of LRP6 is associated with a shortened survival time, for either overall OSCC patients or tongue cancer patient subset." (PMID 28880263, 2017). "Similar relationship between concurrent expression of LRP6/FGF8 and patient outcome was also observed in tongue cancer." (PMID 28880263, 2017).
type 1 diabetes (1 paper, 2011). "Our study was designed to assess association of common single nucleotide polymorphisms (SNPs) in four key genes of the canonical Wnt/β-catenin signalling pathway (AXIN2, CTNNB1, LRP5 and LRP6) with DN using a case-control design involving 1467 individuals with type 1 diabetes." (PMID 21876774, 2011).
tumor (124 papers, 2009 to 2026). "TNBC exhibits increased levels of LRP6 expression, which is linked to tumor-related features such as growth, metastasis, poor prognosis, resistance to chemotherapy, and invasion." (PMID 42087055, 2026). "Its strong association with tumor progression and recurrence highlights p-LRP6 as a candidate marker for poor clinical outcomes of CRC." (PMID 40943055, 2025). "The Wnt receptor, lipoprotein receptor-related protein 6 (LRP6), is associated with cascade signaling, cell proliferation, and tumor growth." (PMID 40569965, 2025). "To test the correlation between LRP6 expression and prognosis of tumor patients, we used univariate Cox regression analysis in order to construct a forest plot and found that LRP6 expression was associated with prognosis in KIRC (HR = 0.574, p = 0.0004)." (PMID 38226972, 2024). "In this study, we found that LRP6 was abnormally highly expressed in a variety of tumors and significantly correlated with microsatellite instability, tumor mutation burden, and immune cell infiltration and immune checkpoint expression in a variety of tumors." (PMID 38226972, 2024). "In an oncogenic context, s2R/TMEM97 is implicated in the Wnt/beta-catenin pathway and upregulates low-density lipoprotein receptor related protein 6 (LRP6) phosphorylation that ultimately results in tumor growth." (PMID 38866499, 2024). "It acts as a chaperone for toll-like receptor (TLR), integrin subunit, and wnt co-receptor low-density lipoprotein receptor-associated protein (LRP6), which are implicated in tumor microenvironment and tumor cell stemness." (PMID 38590708, 2024). "With increasing evidence that LRP6 is closely associated with tumor development and progression, various antibodies, peptides, and small molecules have been developed and show anticancer properties by inhibiting LRP6 function directly or indirectly." (PMID 36983771, 2023). "On the other hand, specific ablation of LRP5 and LRP6 in DCs is associated with delayed tumor progression and enhanced host anti-tumor immunity." (PMID 31684152, 2019). "We generated anti-LRP6 human mAbs and further bsAbs by joining the anti-LRP6 mAb with a guide antibody targeting a tumor-associated antigen, creating a guide/effector bispecific system." (PMID 29335534, 2018). "In contrast, serum supplementation caused a significant induction of LRP6 phosphorylation in both PGCP-depleted tumor cell lines." (PMID 27806330, 2016). "Indeed, as mentioned in this review, upregulated LRP6 function in tumours is frequently associated with cell malignancy, poor prognosis and/or chemoresistance." (PMID 31412666, 2019). "We hypothesized that a bispecific composed of an anti-effector (e.g., anti-LRP6) antibody and an antibody binding to a guide antigen (e.g., a tumor-associated cell surface molecule such as ALCAM, EphA2 or ICAM-1) will modulate potency and cell type selectivity of the anti-effector antibody." (PMID 29335534, 2018). "γ-tocotrienol has shown promise in suppressing tumor growth and stemness by attenuating LRP6 activation." (PMID 40565036, 2025). "In another study, hsa-miR-432 has been shown to act as a tumor suppressor gene by targeting LRP6, TRIM29, and Pygo2, thus deactivating the Wnt pathway." (PMID 38326829, 2024). "Our previous study reported that VSTM2A was an antagonist of Wnt ligands by competitively binding with membrane protein LRP6 and induced LRP6 endocytosis-dependent degradation, which in turn suppressed tumor-intrinsic Wnt/β-catenin signaling activation." (PMID 39289872, 2024). "We further performed KEGG and GO analysis on the differential genes regulated by LRP6 and found that these gene-enriched pathways are closely related to tumor development, such as Ras, ECM, PI3K-AKT and other signaling pathways." (PMID 38226972, 2024). "It was supposed that the cytotoxic activity was due to the reduction in the expression of CTNNB1 and LRP6 genes, which in turn reduces cell proliferation and delays tumor expansion." (PMID 39478959, 2024).
tumor (continued). "It has been reported that oncogenic activation of KRAS/BRAF/MEK signaling stimulates Wnt/β-catenin pathway by β-catenin/TCF4 complex activation via Frizzled co-receptor LRP6 phosphorylation, which in turn promotes tumor growth and invasion." (PMID 37483610, 2023). "GABRB1, PCDHB10, and LRP6 also showed that 80% to 90% of the patients exhibited expression of the biomarker in more than 75% of tumour cells." (PMID 37873862, 2023). "LRP6 is a receptor interacting with the Wnt/β-catenin signaling pathway and participated in regulating cell proliferation and migration of tumor cells." (PMID 37333017, 2023). "Of note, one tumour antigen, a peptide from LRP6, was recognized by bulk T cells after pre-stimulation with both bacterial and microbial peptide and IPdBP peptide pools." (PMID 37198490, 2023). "More importantly, we demonstrated that USP19 catalytic activity is important for the control of tumor cell migration and invasion, and that its molecular mechanism of action involves LRP6, a Wnt co-receptor." (PMID 33714979, 2021). "While two Wnt coreceptors, Lrp5 and Lrp6, are known to be involved in bone homeostasis, they played different roles in tumor progression in our study." (PMID 34230453, 2021). "Several drugs such as salinomycin, prodigiosin, and niclosamide indeed induce LRP6 phosphorylation and degradation leading to decreased tumor growth." (PMID 32850302, 2020). "The results showed that the size of intracranial tumors in miR-137 group was much smaller than that in miR-NC control group after days of implantation, whereas miR-137+LRP6 group showed bigger tumor size after 4 weeks TMZ treatment." (PMID 33718112, 2020). "A soluble LRP6 ectodomain can prevent tumor progression, by inhibiting cell migration and metastasis, by limiting the Frz-mediated non-canonical pathway activation in breast tumor cells." (PMID 32850302, 2020). "Previous studies demonstrate that miR-577 is a well-recognized tumor suppressor and it negatively regulates a lot of oncogenes and oncogenic pathways, including Sphk2, Smurf1, Rab14, Rab25, LRP6, β-catenin, Wnt2b, and so on." (PMID 33069244, 2020). "In situ tumor formation experiment was performed in order to determine roles of miR-137/LRP6 pathway in regulating tumor chemosensitivity to TMZ in vivo." (PMID 33718112, 2020). "LRP6 has been considered as the fundamental drivers of chemoresistance in hepatocellular carcinoma, which closely related to tumor recurrence." (PMID 33718112, 2020). "We found a predominant cytoplasmic expression, both of LRP5 and LRP6, which resulted in the overexpression in 48.6% (107/220) and 44.5% (98/220) of tumor samples, respectively." (PMID 31336689, 2019). "In summary, we revealed that secreted protein VSTM2A is a critical tumor suppressor in colorectal carcinogenesis and a novel antagonist of Wnt signaling receptor LRP6." (PMID 31588233, 2019). "How exactly these β-catenin-independent WNT/LRP6 signaling pathways contribute to tumour development remains to be determined." (PMID 31412666, 2019). "Deletion of LRP5 and LRP6 in dendritic cells markedly delayed tumor growth and enhanced host antitumor immunity by blocking the Wnt pathway." (PMID 31164891, 2019). "MiR-202 and miR-126-3p expression is decreased in HCC tumour tissues, inversely correlating with LRP6 expression." (PMID 31412666, 2019). "This increased LRP6 phosphorylation correlates with tumour malignancy and staging as well as with poor prognosis of CRC, suggesting an important contribution of LRP6 activation in CRC progression and disease outcome." (PMID 31412666, 2019). "Upon conditional knockout of the Wnt co-receptors LRP5 and LRP6 on DCs, DC-mediated anti-tumor immunity is enhanced, ultimately resulting in delayed tumor growth." (PMID 31616443, 2019). "In particular, some tumor samples had high levels of LRP6 RNA and low levels of LRP5 RNA (top left corner), whereas the opposite pattern was observed for others (bottom right corner)." (PMID 29854300, 2018).
tumor (continued). "This polymorphism also was found to reduce the tumor suppressor effect of miR-1269a possibly by attenuating the expression level of miR-1269a in HCC cells and overexpression of target genes SPATS2L and LRP6, and promoted the susceptibility to HCC." (PMID 29467929, 2018). "Conditional knockout of Wnt co-receptors LRP5 and LRP6 on DCs, on the other hand, enhanced DC-mediated anti-tumor immunity leading to delayed tumor growth." (PMID 30619378, 2018). "We found that the depletion of LRP5, LRP6 or STK40 slowed tumor growth in an MDA-MB-468-derived xenograft model." (PMID 29854300, 2018). "Depletions of LRP5, LRP6 or STK40 delayed tumor growth to similar extents in a statistically different manner." (PMID 29854300, 2018). "NDN affects tumor cell proliferation in CRC by inhibiting the expression of LRP6, which is a key factor in the activation of the Wnt signaling pathway." (PMID 28521288, 2017). "It was noteworthy that positive p-LRP6 was usually observed at the invasive front tumor zone in infiltrating nests of cancers." (PMID 29312635, 2017). "The correlations between p-LRP6 expression and clinicopathologic parameters such as age, gender, tumor size, depth of invasion, lymph node metastasis, TNM and Dukes staging were analyzed." (PMID 29312635, 2017). "Along this line of evidence, the application of soluble recombinant LRP6 extracellular domain effectively inhibited the appearance of metastatic foci from otherwise aggressive metastatic tumor cells." (PMID 28418856, 2017). "In contrast to well-differentiated tumor, a higher level of LRP6 was found to be in the poorly and moderately differentiated (ANOVA; well differentiated 18, moderately differentiated 5, poorly differentiated 5; P=0.0056)." (PMID 28880263, 2017). "Previously, we found the up-regulated expression of CCN2 and LRP6 in oxaliplatin-resistant subcutaneous tumor mice screened by cDNA microarrays." (PMID 28870205, 2017). "Actin skeleton seemed to be rearranged upon LRP6 overexpression and enabled tumor cells to gain increased migratory capability." (PMID 29312635, 2017). "As LRP6 is a co-receptor for Wnt in the canonical Wnt/β-catenin signaling, and the up-regulation of LRP6 phosphorylation induces tumor metastasis, we next examined the regulation of phospho-LRP6 by PGCP." (PMID 27806330, 2016). "(ii) In contrast, significantly down-regulated genes from another group were associated with tumor metastasis suppression (KISS1), retinoblastoma (Rb) gene positive regulator (CCND1), and a canonical Wnt antagonist (LRP6 through DDK1)." (PMID 26079538, 2015). "In general, four of our myc-CA LRP6 overexpressing clones showed more aggressive tumor phenotype in terms of the cell proliferation, migration, invasion and tumorigenicity assays." (PMID 22570728, 2012). "With immunohistochemistry, strong positive staining of LRP6 was seen in the cytoplasm (white arrows) and cell membranes (black short arrows) of the tumor cells." (PMID 22570728, 2012). "Inhibition of LRP6 function in Rad6B-overexpressing subpopulations resulted in a significant decrease of tumor growth (P = 0.01) as compared to R6B-Zshigh cells." (PMID 21767405, 2011). "Endogenous autocrine Wnt signaling in different tumor cell lines can be either antagonized or enhanced by the LRP6 antibodies, indicating expression of different Wnt isoforms." (PMID 20856934, 2010). "In Wnt-driven xenograft and allograft tumor models, the LRP6 antibodies inhibit Wnt signaling and tumor growth in a Wnt isoform-specific manner predicted by their properties characterized in cell culture." (PMID 20856934, 2010). "Individual LRP6 antibodies can inhibit autocrine, or endogenous, Wnt signaling in some tumor cell lines and potentiate autocrine signaling in other tumor cells, likely because the cell lines express different Wnt isoforms." (PMID 20856934, 2010).
tumor (continued). "Lrp6 heterozygosity slightly delayed the time at which tumors first appeared, but the rate of tumor onset was then similar between Lrp6+/− and Lrp6+/+ females." (PMID 19503830, 2009). "Moreover, 45–75% of HCC tumor samples reveal elevated LRP6 expression compared to normal liver tissue." (PMID 40943055, 2025). "This relationship could be crucial for understanding LRP6′s role in tumor growth and progression, potentially making it a target for therapeutic intervention in highly proliferative NETs." (PMID 39796676, 2024). "Additionally, immunofluorescence assay demonstrated an enhanced co-localization of IGFBP2 and LRP6 in the mouse tumor tissues." (PMID 37957694, 2023). "The expression of OSMR and LRP6 in tumor cells and SERPINF1 in stromal cells was detected by IHC." (PMID 37333017, 2023). "Finally, the coreceptors LRP5 and LRP6 are key receptors for the activation of canonical WNT signaling, and specific deletion of LRP5 and LRP6 in DCs is associated with delayed tumor progression and enhanced host antitumor immunity." (PMID 36358276, 2022). "In addition, low-density lipoprotein receptor-related protein 6 (LRP6) is considered a tumor promoter." (PMID 36106333, 2022). "Curcumin down-regulated Wnt/β-catenin signaling by suppressing Wnt3a and low-density lipoprotein receptor-related protein 6 (LRP6) phosphorylation - an event critical for the activation of the pathway - as well as downstream target genes contributing to tumor growth, such as c-myc." (PMID 35685638, 2022). "Heat shock protein (HSP) GRP94, also known as GP96, is an ER paralog of HSP90 and has been shown to promote survival signaling during tumor-induced stress and modulate the immune response through its multiple clients, including TLRs, integrins, LRP6, GARP, IGF, and HER2." (PMID 33898309, 2021). "Overexpression of LRP6 in the mammary glands of mice initiated tumor formation." (PMID 34615853, 2021). "Taken together, the α19BBZ-LRP6 CAR-T cells may have a similar capacity of tumor cell lysis, while the overexpression of LRP6 with anti-CD19 CAR exhibited a greater memory T cell population and lower apoptosis of the T cell population after stimulation." (PMID 33042788, 2020). "Immunohistochemistry assay results of LRP6 and Ki-67 expressions in three groups also showed that LRP6 could reverse the inhibited ability of tumor proliferation by miR-137 in vivo." (PMID 33718112, 2020). "And high circ-LRP6 was positively correlated with larger tumor size and later TNM stage." (PMID 32867570, 2020). "In agreement with the tumor formation, the weight of tumors from miR-137 overexpression group were significantly smaller than those from the miR-NC overexpression group, while the tumor size from miR-137+LRP6-overexpression group was much bigger than that from miR-137 overexpression group." (PMID 33718112, 2020). "Besides, circ-LRP6 was recently proposed as a tumor-promoting circRNA in osteosarcoma by negatively regulating KLF2 and APC expression." (PMID 32867570, 2020). "Lastly, we tested the effect of circ-LRP6 in vivo by establishing xenograft tumor model." (PMID 32867570, 2020). "Indeed, reducing LRP6 expression and/or activity inhibits cancer cell proliferation and delays tumour growth in vivo." (PMID 31412666, 2019). "Given the high incidence of HBV in HCC development, targeting LRP6 could be an efficient therapeutic strategy to limit tumour development in this context." (PMID 31412666, 2019). "Although no mutation has been reported in LRP6, 45–75% of HCC tumour samples harbor increased LRP6 expression in comparison to normal liver tissue." (PMID 31412666, 2019). "Notably, exogenous administration of a MESD peptide in a MMTV-WNT1 tumour mouse model suppressed tumor growth in vivo, likely through peptide binding to mature LRP6 at the cell surface and interference with ligand binding." (PMID 31412666, 2019). "Antibodies targeting LRP6 or Fzd7 have been reported to display anti-tumor activity in vivo." (PMID 29854300, 2018).